AR (androgen receptor)
Diseases named in the same sentence as AR in open-access papers (continued):
Sharing a sentence is not in itself a finding about the gene and the disease.
prostate carcinoma (continued). "As the results above indicate HUVEC could suppress AR expression and our previous data showed that AR function as suppressor of autophagy in AR positive prostate cancer cells, we are curious whether HUVEC could induce autophagy directly and drugs targeting autophagy could attenuate cell invasion." (PMID 30200999, 2018). "Recent preclinical and clinical studies have shown that in response to successful androgen/AR blockade, AR-positive prostate cancers may switch to androgen/AR-independent pathways for survival and growth, thereby conferring therapy resistance and enabling disease progression." (PMID 30478344, 2018). "This study identified a novel downstream effector of V-ATPase in prostate cancer cells; our results show for the first time that androgen receptor expression is V-ATPase-dependent, and we present a cellular mechanism that links V-ATPase to AR expression and activity." (PMID 29988966, 2018). "Since ERRα can cross-talk to AR signaling by its direct transactivation of common ARE-containing AR targets, it could be likely that the transactivation of T:E fusion gene by ERRα could be indirectly mediated through its interference on AR signaling in prostate cancer cells." (PMID 30042415, 2018). "Also, it is reported that upregulation of PI3K/AKT, Wnt/B-catenin and IGF1 signaling pathways may contribute to activation of AR signaling and aggressiveness in African-American prostate cancer." (PMID 28039468, 2017). "For example, abiraterone (an androgen biosynthesis inhibitor) and enzalutamide (an AR blocker) are both approved for treatment of castration resistant prostate cancer and have demonstrated a survival advantage in chemotherapy-naive and chemotherapy refractory prostate cancer patients." (PMID 27741511, 2017). "Epigenetic drift may further give rise to clones with different AR transcriptional programs, giving different selective advantages during carcinogenesis and progression, and serve as a basis for heterogeneity in PCa and prostate cancer stem cells." (PMID 28446230, 2017). "Interestingly, PC-3 and DU145 cells express functional glucocorticoid receptors (GR) and a recent study showed that GR could substitute for AR function and contributes to CR in prostate cancer." (PMID 28270124, 2017). "Although prostate cancer is considered an androgen-driven pathology, particularly in the early stages, a number of studies have reported the existence of a cell population with diminished AR activity, and corresponsibly reduced prostate-specific antigen (PSA) expression." (PMID 28038472, 2017). "Androgens bind to the androgen receptor (AR), with the latter acting as a transcription factor to regulate the expression of androgen response genes that modulate many cellular activities such as proliferation and apoptosis to contribute to prostate cancer development and progression." (PMID 28493878, 2017). "In addition, AR signalling is integral to the development and progression of prostate cancer." (PMID 27653015, 2017). "Unlike advanced prostate cancer cells, androgen receptor splice variant 7 (AR-V7) cannot be detected in U87 or U251 cells suggesting glioma cells may sensitive to androgen receptor agonist or antagonist." (PMID 28423563, 2017). "Notably, AR is critical for PCa progression and considered as a key factor for delaying the progression from androgen-dependent prostate cancer to castrate-resistant prostate cancer." (PMID 28968984, 2017). "Collectively, the specific expression pattern of NRIP, AR and DDB2 in the cribriform type of human prostate cancer is consistent with our hypothesis that NRIP protects against AR degradation by DDB2 in the CUL4-DDB1 E3 ligase complex, in at least a subset of prostate cancers." (PMID 28212551, 2017).
prostate carcinoma (continued). "Besides, the lately study elaborated that PCGEM1 and PRNCR1, bound successively to the androgen receptor and strongly enhanced both ligand-dependent and ligand-independent androgen-receptor-mediated gene activation programs and proliferation in prostate cancer cells." (PMID 28915709, 2017). "Additionally, we demonstrated that androgen-induced CREB3L4 expression is in part regulated by AR directly, and in part indirectly, by IRE1α signaling, suggesting that a distinct AR-ER stress-CREB3L4 regulatory axis also plays a role in prostate cancer proliferation." (PMID 28338058, 2017). "In addition, AR could stimulate DNA replication via hyperphosphorylated RB indirectly in prostate cancer cells." (PMID 29261702, 2017). "Our results suggest that there are separate basal and luminal stem cell populations in the prostate, and they open up the possibility that androgen receptor-expressing luminal stem-like cells could function as cancer-initiating and relapse-responsible cells in prostate cancer." (PMID 28446230, 2017). "A recent study found that CEBPA promotes castration-resistance and AR signaling in prostate cancer through a direct protein interaction with AR; this suggests that co-targeting CEBPA and AR may be one approach to block AR in either castration-resistant or enzalutamide-resistant tumors." (PMID 29340039, 2017). "In general, folding of AR to a mature hormone binding conformation is a highly ordered, dynamic assembly of heteromeric complexes that involves multiple chaperone and co‐chaperone components, most of which represent potential targets for the treatment of prostate cancer." (PMID 28252832, 2017). "Thus, the control of AR expression as well as its co-effectors and downstream players may have significant effect on prostate cancer metastasis." (PMID 28430640, 2017). "Lei Li and other researchers have found that after androgen blockade therapy in prostate cancer, a large number of mast cells can aggregate in the tumor microenvironment and then increase the number of stem cells and progenitor cells through the downstream androgen receptor signaling pathway." (PMID 28245841, 2017). "Therefore, we were interested in examining the NRIP, DDB2 and AR protein expression profiles in human prostate tumors with the aim of elucidating the interaction mechanism of these three proteins and their roles in prostate cancer." (PMID 28212551, 2017). "Therefore, distinct mechanisms may underlie co-regulator functions in bladder cancer versus other AR-positive malignancies such as prostate cancer." (PMID 28241422, 2017). "Continued growth of metastatic prostate cancer cells during complete androgen blockade, in both clinical and experimental settings, is the result of mechanisms permissive for continued function of AR and/or those of its activated pathways despite combined AR/androgen targeting." (PMID 28117763, 2017). "Thus, androgen may repress PKD1 through an AR-induced FGFR/FRS2/MEK/ERK pathway to inhibit PKD1 expression in prostate cancer cells." (PMID 28077787, 2017). "Furthermore, PKC driven AR phosphorylation may promote prostate cancer progression and provide a novel therapeutic target." (PMID 27902483, 2017). "This study not only identifies Androgen Receptor as a target of RNase L regulation, but also demonstrates that the effect of HPC1-associated mutations on AR signaling and cell migration is amenable to regulation by physiological conditions that exist in prostate cancer cells." (PMID 28257035, 2017). "Thus, we speculated whether CREB3L4 may also play a critical role in regulating prostate cancer cell proliferation, through interacting with AR." (PMID 28338058, 2017). "Hence, we conclude that USP14 promotes prostate cancer progression likely through stabilization of AR, suggesting that USP14 could be a promising therapeutic target for prostate cancer." (PMID 28151478, 2017).
prostate carcinoma (continued). "In addition, sGCα1 protein is over-expressed in both AR-expressing prostate cancer cells and prostate tumors, while sGCβ1 is weakly expressed, showing that there is a significant pool of endogenous sGCα1 that is free of sGCβ1 and therefore it is possible that Peptide B-8R targets this sGCα1 protein." (PMID 28859127, 2017). "Moreover, AR inhibition can activate Akt signaling by reducing levels of AKT phosphatase PHLPP in prostate PTEN-deficient murine prostate cancer model and in human prostate cancer xenografts." (PMID 28400729, 2017). "In summary, we propose that NRIP and DDB2, through competitive binding to the AR, antagonize each other's function in maintaining AR homeostasis and disruption of the balance between these two proteins may contribute to the pathogenesis of a specific type of aggressive prostate cancer." (PMID 28212551, 2017). "However, the signaling pathway that regulates filamin A cleavage and cell migration in AR- deficient prostate cancer cells has not been studied." (PMID 27206800, 2017). "In summary, in this study we bring evidence that N-cadherin upregulation in prostate cancer cells appears to result from the binding of AR variants to AREs in intron 1 of the CDH2 gene followed by histone H4 acetylation, but also from a decrease of endogenous AR-FL." (PMID 29069764, 2017). "The AR holds important roles in normal prostate development and physiology, in the maintenance of secondary male characteristics, and in sexual function in the adult male; however, its dysregulation is also largely responsible for prostate cancer (PCa) development and progression." (PMID 28038451, 2017). "Presumably, there may be an interaction between AR and GRβ in prostate cancer." (PMID 27036026, 2016). "BCL acts as an antagonist in prostate cancer cells with an AR (T877A) mutation but FLT does not." (PMID 27493956, 2016). "Importantly, prostate cancer cells are capable of metabolizing the testosterone found in FBS into dihydrotestosterone (DHT) at concentrations similar to those found in CRPC tumors (~1–10 nM) that promote AR function and CRPC growth." (PMID 27276681, 2016). "Indeed, prostate cancer cells that express AR showed greater sensitivity to inhibition of growth by AIL at lower concentration, suggesting the degradation of AR by AIL plays a major role in inhibiting cell growth of AR-positive prostate cancer cells at low concentrations of AIL." (PMID 27959342, 2016). "Moreover, we determined whether DNACR regulated cell invasion synergistically with EZH2 and whether DANCR affected the effect of androgen-AR signaling and enzalutamide, an inhibitor of AR, on migration and invasion of prostate cancer cells." (PMID 27191265, 2016). "Taken together, our results support that AR could inhibit some metastasis-promoting pathways or molecules in prostate cancer, and suggest that knockdown of DANCR could lessen the side effect of AR inhibitor, which may be useful in the treatment of prostate cancer." (PMID 27191265, 2016). "Thus, we speculate that overexpression of miR-449a or knockdown of c-Myc may inactivate AR signaling and then increase the radiosensitivity of prostate cancer cell to ionizing radiation." (PMID 27250340, 2016). "We further investigated whether DANCR affects AR function on the invasion of prostate cancer cells." (PMID 27191265, 2016). "Given that vorinostat and bicalutamide both target AR, we initially hypothesized that the combination of these two agents would enhance blockade of androgen signaling, a pathway that promotes growth and survival of prostate cancer cells." (PMID 26907477, 2016). "Given that many clinical prostate cancers are characterized by aberrant AR signaling, and that intra-tumoral heterogeneity may result in foci that each potentially have structurally different androgen receptors, this is a promising feature of the combination therapy." (PMID 26907477, 2016). "Also, androgen receptor (AR) profiling predicts prostate cancer outcome." (PMID 27895806, 2016).
prostate carcinoma (continued). "Thus, the decrease in cell growth produced by TQ in androgen-sensitive prostate cancer cell lines may be due at least in part to the action of TQ to down-regulate AR expression." (PMID 26986969, 2016). "In addition, other studies in prostate cancer demonstrated that AR may regulate the decrease in TGFBR2 levels through micro-RNA-21." (PMID 26091707, 2016). "Interestingly, LMTK2 negatively regulates AR expression in prostate cancer cells and decreased expression of LMTK2 has been observed in prostate cancer, indicating that the regulatory mechanisms between AR and LMTK2 in RCC and prostate cancer may be different." (PMID 26814892, 2016). "Additionally, RNA analysis of enriched CTC fractions have been performed using reverse transcription PCR (RT-PCR) amplification of tumor-specific transcripts, such as AR splice variant 7 in CRPC, and translocations like EML4–ALK in lung cancer and TMPRSS2–ERG in prostate cancer." (PMID 26980749, 2016). "Moreover, in androgen receptor (AR)-positive models, ERRα has been implicated in AR signaling pathways and shown to increase HIF-1 signaling and to promote hypoxic growth adaptation of prostate cancer cells." (PMID 27776343, 2016). "Studies of AR chromatin binding by chromatin immunoprecipitation (ChIP) approaches like ChIP-on-chip or ChIP in combination with next generation sequencing (ChIP-Seq) have shed light onto the mechanisms of global regulation of AR activities in prostate cancer cell lines or tissues." (PMID 27623747, 2016). "Thus, this study points to an ACLY-AMPK-AR network that could potentially be targeted to increase the efficacy of current AR-targeted therapies, by impacting metabolic dependencies of prostate cancer cells." (PMID 27248322, 2016). "AR signaling may retain similar functional roles in prostate cancer stem progenitor (S/P) cells." (PMID 27203692, 2016). "Therefore, prostate cancer samples with increased AR levels had increased KLF4 expression." (PMID 27991915, 2016). "We have identified a novel mechanism by which ADRB2 may indirectly regulate the activity of the androgen receptor in prostate cancer cells, namely through regulating glucuronidation, a critical step in the extrahepatic phase II metabolic elimination pathway of androgens." (PMID 26646591, 2016). "Thus, these SPOP mutants could enhance AR functions in prostate cancers by inhibiting the turnover of both AR and its coactivator SRC-3." (PMID 27200299, 2016). "Another meta-analysis in 2012 reported that AR CAG repeat polymorphism with ≥20 repeats might confer a protective effect among prostate cancer patients older than 45 years, but not all prostate cancer patients." (PMID 26421011, 2015). "Therefore, although PBK expression is strongly associated with higher-grade prostate cancer, we hypothesize that PBK's expression is driven by a factor other than the AR." (PMID 25909225, 2015). "Key among the findings which may account for the aberrant activation of the AR in prostate cancer was the discovery that, in addition to classical ligand-binding mechanisms, transcriptional activity of the AR is controlled through its direct binding to the RhoA effectors PRK1 and PRK2." (PMID 26296974, 2015). "Reactivation of androgen receptor (AR) may drive recurrent prostate cancer in castrate patients." (PMID 25950519, 2015). "Additionally, AR transcriptional activity is frequently co-opted by gene fusion events during prostate cancer (PCa) development and progression, as exemplified by AR-dependent ERG overexpression caused by fusion of the ERG gene body to the AR-regulated TMPRSS2 promoter." (PMID 25908785, 2015).
prostate carcinoma (continued). "Our results demonstrate that AR inhibits autophagy via transactivation of miR-101, thus combination of miR-101 mimics with celastrol may represent a promising therapeutic approach for treating prostate cancer." (PMID 26473737, 2015). "Indeed, the AR-mediated mechanisms responsible for cyclin D1 and D2 down-regulation by androgen in HPr-1AR differ from the post-transcriptional mechanism that reportedly increases cyclin D1/2 expression in LNCaP prostate cancer cells." (PMID 26372468, 2015). "In addition to AR signaling, the PI3K/Akt/mTOR pathway is associated with prostate cancer." (PMID 26506516, 2015). "However, emerging evidence suggests that TCDD may inhibit androgen receptor signaling and prostate cancer progression." (PMID 26154658, 2015). "AR status could affect miR-101 expression in human prostate cancer cells." (PMID 26473737, 2015). "Previous work has also implicated p110β as a positive regulator of AR transactivation in prostate cancer cell lines and PI3K/mTOR signalling has been shown to either positively or negatively modulate AR transactivation both in prostate cancer cell lines and genetic mouse models of prostate cancer." (PMID 26132308, 2015). "Therefore, agents that block the interaction of AR and p52 could potentially prevent the progression and/or inhibit the growth of castration-resistant prostate cancer." (PMID 26622945, 2015). "This phosphorylation of AR may lead to Mdm2-mediated protein degradation in prostate cancer cells." (PMID 26318424, 2015). "Moreover, BPA may also interact with other steroid receptors (such as androgen receptor) and plays a role in prostate cancer development." (PMID 25569640, 2015). "Androgen activation of stably expressed AR has been shown to inhibit the proliferation of HPr-1 immortalized human prostate epithelial cells, HPrE human prostate basal epithelial cells, mPrE mouse prostate basal epithelial cells, and PC-3 prostate cancer cells." (PMID 26372468, 2015). "Given the effects of p23 upon AR activity and stability (and vice‐versa) and since prostate cancer is an AR‐driven malignancy, we next investigated whether p23 may also be involved in promoting prostate cancer progression." (PMID 25241147, 2015). "Thus, AR pathway plays animportant role in regulation of CX43 expression in prostate cancer cells." (PMID 26491675, 2015). "Therefore, AR may be the common target for IL-6 and miR-21 in prostate cancer, with miR-21 playing an intermediary role in activating IL-6 to regulate PDCD4 expression." (PMID 26252635, 2015). "Studies to further delineate the mechanism of action of AR/p52-02 and/or analogues may help further the understanding of how AR and p52 are important in castration-resistant prostate cancer and potentially unearth additional pathway(s) targets for development of therapies for prostate cancer." (PMID 26622945, 2015). "Thus HBC inhibits AR transcriptional activity as effectively as Casodex in prostate cancer cells." (PMID 25704883, 2015). "Furthermore, loss of LMTK2, associated with prostate cancer can enhance AR transcriptional activity in absence of androgen, suggesting role of LMTK2 in development of CRPC." (PMID 26008968, 2015).